TOR1A (torsin family 1 member A)
Diseases named in the same sentence as TOR1A in open-access papers (continued):
Sharing a sentence is not in itself a finding about the gene and the disease.
Dystonia (continued). "Interestingly, one late-onset PD patient (age at onset >70 years) without dystonia, carrying the pathogenic TOR1A p.Glu303del variant, had a mother with PD, but also one daughter and two grandchildren with dystonia." (PMID 40672488, 2025). "As more genetic etiologies are identified for dystonia, it has become clear that anatomic distribution relates strongly to genotype, with some genes (e.g., GNAL) typically causing a craniocervical-predominant syndrome, while craniocervical involvement is less frequent in others (e.g., TOR1A)." (PMID 37920445, 2023). "TOR1A-associated arthrogryposis multiplex congenita 5 (AMC5) is a rare neurodevelopmental disorder arising from biallelic variants in TOR1A, a gene that in the heterozygous state is associated with torsion dystonia-1 (DYT1 or DYT-TOR1A), an early-onset dystonia with reduced penetrance." (PMID 36757831, 2023). "Our observation of a chronic elevation in neuronal cAMP in the striatum of Tor1a+/− can open a new window to investigate the role of cAMP changes in the severely altered synaptic plasticity of medium spiny neurons and cholinergic interneurons in dystonia mouse models." (PMID 33799994, 2021). "For DYT1 dystonia, future studies exploring a therapeutic critical period for Tor1a gene replacement will require novel genetic tools for reactivation and/or supplementation of torsinA expression in DYT1 dystonia model systems at different developmental stages." (PMID 33616084, 2021). "In Tor1a+/−, opposite changes of A2A receptors’ expression in the striatal-pallidal complex and the entopeduncular nucleus suggest that the pathophysiology of dystonia is critically dependent on a composite functional imbalance of the indirect over the direct pathway in basal ganglia." (PMID 33799994, 2021). "The high distribution of adenosine A2A receptors in the striatum and globus pallidus of control Tor1a+/+ mice and their selective increase in the same areas of Tor1a+/− mice suggest a major role of A2A within the indirect pathway for basal ganglia physiology and dystonia pathophysiology." (PMID 33799994, 2021). "Hence, we may be unable to detect disease-relevant genetic interactions of DYT genes that are likely to generate dystonia through a fundamental role during brain development, such as TOR1A, THAP1 and KMT2B." (PMID 32889528, 2020). "Thus, the missense polymorphism Asp216His (rs1801968) in the TOR1A (DYT1) gene serves to moderate the clinical impact, in both cis and in trans, of the TOR1A c.904-906 del GAG mutation, the major mutation underlying early-onset dystonia." (PMID 23820649, 2013). "The precise functions of these genes and the degree to which their activities may overlap are not known, though TOR1A is notable for causing early-onset dystonia due to a codon deletion that removes a particular glutamic acid residue from the torsinA protein." (PMID 22022556, 2011). "A genetic etiology was identified in 17 patients [eight harboring TOR1A (DYT1), five harboring THAP1 (DYT6), and four harboring KMT2B (DYT28)] while the rest had idiopathic dystonia (n = 16)." (PMID 32322234, 2020). "Remarkably, we observed an enhancement of pro-BDNF and BDNF protein level in P26 Tor1a+/Δgag mice, which appears critical for the onset of abnormal neurophysiological phenotype in DYT1 dystonia." (PMID 29504938, 2018). "DYT1 dystonia is a form of early onset isolated dystonia stemming from a three base pair deletion (∆GAG) in the TOR1A gene in humans." (PMID 28659770, 2017). "Therefore, understanding the mechanisms and roles of the synaptic transport pathway involving TorsinA is crucial and can provide new ideas and methods for the prevention and treatment of DYT- TOR1A dystonia." (PMID 37638318, 2023). "In particular, our findings show that α‐Syn is downregulated in the striatum of mutant Tor1a+/Δgag mice but not in a distinct dystonia model, the DYT25 GNAL rat model." (PMID 35420219, 2022).
Dystonia (continued). "Similar reductions in cortical inhibition were found in segmental and generalised forms of dystonia and non-manifesting carriers of TOR1A/DYT1, further supporting the notion of abnormal endophenotypes in dystonia." (PMID 32638036, 2020). "To investigate the role of peripheral stressors we specifically chose the Tor1a+/- mouse model since it does not develop overt dystonia nor any signs of neurodegeneration." (PMID 27716431, 2016). "However, in practice, this has not happened and both clinicians and researchers alike tend to use dystonia loci and genes names interchangeably, e.g. DYT1/TOR1A or DYT6/THAP1." (PMID 23775978, 2013). "Several other SNPs are present in the 5′ and 3′ UTR regions of TOR1A, as well as a single-base-pair deletion in the 3′ UTR (G-del), but these features are not known to be associated with the penetrance of DYT1 dystonia." (PMID 22393392, 2012). "Furthermore, symptoms of abnormal motor learning have also been observed in Tor1a mutation (Tor1a+/-) carriers without evident clinical manifestation, which further supports the opinion that impaired synaptic plasticity might be an inherent feature of dystonia." (PMID 34398825, 2021). "By treating Tor1a+/- mice with either L-Dopa or the DA synthesis blocker AMPT we could drive striatal DA concentrations into opposite directions and either aggravate or reduce dystonia-like movements in the mutant mice as compared to those observed with no treatment." (PMID 27716431, 2016). "However, in keeping with our observation of an increase in DA neurotransmission in nerve injured, dystonic Tor1a+/- mice approaching wt baseline level, one would expect none or only mild DA metabolic changes comparing dystonia manifesting DYT1 patients with healthy subjects." (PMID 27716431, 2016). "Using a principal component analysis approach to identify a specific dystonia-related metabolic pattern (DYT-RP) revealed, not surprisingly, an increased DYT-RP expression in TOR1A and THAP1 MCs and a reduced expression in NMCs even when compared to controls." (PMID 33486625, 2021). "Sensory temporal discrimination is also prolonged non-manifesting TOR1A/DYT1 carriers and unaffected first-degree relatives of dystonia sufferers in a frequency suggestive of an incompletely penetrant dominant gene, supporting an endophenotypic role for abnormal temporal discrimination in dystonia." (PMID 32638036, 2020).
generalized dystonia (23 papers, 2009 to 2026). "In 1997, the TorsinA (TOR1A) gene was the first to be identified as the major cause for young-onset (primary) generalized dystonia." (PMID 34149592, 2021). "As an example, for early-onset generalized dystonia caused by mutations in the TOR1A gene, the designation has changed from DYT1 to DYT-TOR1A." (PMID 33604773, 2021). "Mutations in the Tor1A gene are the most common genetic cause of childhood‐onset generalized dystonia." (PMID 27061943, 2016). "DYT1 early-onset generalized dystonia is a hyperkinetic movement disorder caused by mutations in DYT1 (TOR1A), which codes for torsinA." (PMID 21931745, 2011). "Another mutation in Exon 5 of TOR1A (c.863G>A) has been described in a female patient with severe childhood-onset generalized dystonia." (PMID 19284587, 2009). "Although the c.904_906delGAG mutation in Exon 5 of TOR1A typically manifests as early-onset generalized dystonia, DYT1 dystonia is genetically and clinically heterogeneous." (PMID 19284587, 2009). "The ΔGAG (c.904_906delGAG) mutation in Exon 5 of TOR1A is characteristically associated with early-onset generalized dystonia." (PMID 19284587, 2009). "Interestingly, one patient with early‐onset generalized dystonia harbored two known likely pathogenic variants in different genes (TOR1A:p.Arg288Gln and SPAST:p.Glu418del)." (PMID 40533913, 2025). "One well-studied example from the myriad of genetic dystonias is DYT1, a severe generalized dystonia with typical onset in mid-childhood, resulting from a mutation in TOR1A, (typically a three base pair deletion leading to loss of a glutamic acid residue at the carboxyl-terminal region)." (PMID 34367047, 2021). "DYT1, the most common inherited, early-onset, generalized dystonia, is caused by dominant mutations in the gene TOR1A which encodes the protein torsinA." (PMID 22880064, 2012). "Although commonly associated with childhood-onset generalized dystonia, DYT1 due to the classic ΔGAG deletion in TOR1A, may manifest as an M-D-like syndrome." (PMID 33200041, 2020). "Although we did not remove cases with known genetic syndromes (i.e., TOR1A), our cohort was limited to those over 18, while a cohort including pediatric participants would likely include more genetically confirmed generalized dystonia." (PMID 37920445, 2023). "To help address the role of the TOR1A gene in non-generalized primary dystonia, we used high resolution melting (HRM) to examine the entire TOR1A Exon 5 coding sequence in a large cohort of patients with non-generalized dystonia." (PMID 19284587, 2009).
Torsion dystonia (15 papers, 2007 to 2024). Sustained involuntary muscle contractions that produce twisting and repetitive movements of the body. "Most cases of early onset torsion dystonia (DYT1) are caused by a 3-base pair deletion in one allele of the TOR1A gene causing loss of a glutamate in torsinA, a luminal protein in the nuclear envelope." (PMID 29396398, 2018). "For example, polymorphisms in the TOR1A/TOR1B region are associated with torsion dystonia, a neurological disorder characterized by debilitating muscle contractions." (PMID 27755386, 2017).
Parkinson disease (14 papers, 2011 to 2025). A progressive degenerative disorder of the central nervous system characterized by loss of dopamine producing neurons in the substantia nigra and the presence of Lewy bodies in the substantia nigra and locus coeruleus. "The A2A mRNA changes in the basal ganglia of Tor1a+/− appear to be specific, since in Parkinson’s disease A2A mRNA appears either decreased in the striatum or unchanged in the globus pallidus." (PMID 33799994, 2021). "Variants in none of the five implicated dystonia genes (TOR1A, SGCE, GNAL, THAP1 and KMT2B) have been reported to cause PD/parkinsonism to date." (PMID 39087914, 2024).
idiopathic dystonia (7 papers, 2013 to 2025). "Oppenheim dystonia (DYT-TOR1A) is caused by a specific 3-base pair deletion “GAG” in the coding region for TorsinA in the TOR1A gene." (PMID 35207493, 2022).
depression (6 papers, 2012 to 2025). "Additionally, symptoms of depression are a prevalent complaint in isolated adult-onset dystonia and hereditary dystonia types as e.g. TOR1A carriers have a higher risk of recurrent major depressive disorder than non-carriers." (PMID 41016940, 2025). "Those involving THAP1 (n = 1) and TOR1A (n = 1) were linked with myelopathies, while SGCE variants (n = 2) were associated with depression, anxiety and myoclonus, and hemiplegia for the single overlapping TH variant." (PMID 35925398, 2022). "TOR1B, which shows immunoreactivity in all subfields of the hippocampus, is homologue to TOR1A (alternative name: DYT1), is associated with early-onset recurrent major depression and is involved in the regulation of dopamine release." (PMID 22701688, 2012).
focal dystonia (5 papers, 2009 to 2026). A dystonia that is localized to a specific part of the body. "Our meta-analysis revealed a significant implication of rs1182 and rs1801968 TOR1A variants in the development of focal dystonia and writer’s cramp respectively." (PMID 28081261, 2017). "Our study detected a significant influence of a specific variant of TOR1A gene, rs1182, on the risk of focal dystonia." (PMID 28081261, 2017). "In conclusion, our meta-analysis revealed a possible influence of rs1182 TOR1A SNP on the risk of focal dystonia and of rs1801968 on the risk of writer’s cramp." (PMID 28081261, 2017). "The TOR1A, KMT2B, or WASHC5 mutations were identified as causative gene in three patients with childhood-onset focal dystonia." (PMID 35719373, 2022). "Further large-scale collaborative studies in different ethnic groups, with larger samples and with prospective and gene-environment interaction design are of great necessity in order to elucidate the role of TOR1A gene in focal dystonia." (PMID 28081261, 2017).
blepharospasm (4 papers, 2009 to 2023). "Blink reflex R2 inhibition is abnormally decreased in patients with cranial, cervical, segmental and generalised dystonia including those without blepharospasm and is present equally in manifesting and non-manifesting TOR1A/DYT1 carriers." (PMID 32638036, 2020).
myoclonus dystonia (3 papers, 2017 to 2024). "Analysis of the TOR1A, THAP1, and SGCE genes excluded dystonia type 1, 6 (DYT1, DYT6) and myoclonus dystonia (DYT11)." (PMID 38916623, 2024).
Onset (3 papers, 2009 to 2018). The age group in which disease manifestations appear. "A three-base-pair deletion in the human TOR1A gene is causative for the most common form of primary dystonia: the early-onset dystonia type 1 (DYT1 dystonia)." (PMID 29739751, 2018).
arthrogryposis (2 papers, 2023 to 2025). A rare, non-progressive congenital disorder characterized by multiple joint contractures which are present at birth. "A diagnosis of TOR1A-related arthrogryposis was made based on the characteristic phenotype and segregation of a recurrent pathogenic TOR1A variant in both parents." (PMID 36757831, 2023).
developmental delay (2 papers, 2019 to 2023). "In conclusion, autosomal-recessive TOR1A-related disorders span a wide phenotypic spectrum, ranging from mild motor symptoms to severe arthrogryposis, global developmental delay and early death." (PMID 36757831, 2023).
Intellectual disability (2 papers, 2018 to 2025). "Intellectual disability was universally present in individuals with variants in ZC4H2 (5/5), DYNC1H1 (4/4), TOR1A (2/2), KAT6B (1/1), GLDN (1/1), and GPC3 (1/1), signifying a strong association between these genes and cognitive deficits." (PMID 40443119, 2025). "Cognitive involvement, including individuals with intellectual disability and/or autism spectrum disorder, was observed in 27% of cases (27/100), mostly associated with pathogenic variants in DYNC1H1, TOR1A, and ZC4H2." (PMID 40443119, 2025). "The observation of specific genotype–phenotype correlations, such as the increased association of intellectual disability with variants in DYNC1H1, ZC4H2, and TOR1A, is valuable for early prognosis and family counseling." (PMID 40443119, 2025). "For instance, SPTAN1 gene deletion in chromosome 9:(130900001–133,080,000) has been reported to be associated with early infantile epileptic encephalopathy, infantile spasms, intellectual disability, and hypomyelination, and molecular defects of TOR1A gene lead to early-onset primary dystonia." (PMID 30038665, 2018).
steatosis (2 papers, 2020 to 2024). Increased lipid within the cytoplasm of cells. "We had shown previously that mice with depletion of only 1 Tor1a allele with approximately 50% reduction of torsinA do not develop steatosis." (PMID 38194265, 2024).
arthrogryposis multiplex congenita 5 (1 paper, 2023). "TOR1A-associated arthrogryposis multiplex congenita 5 (AMC5, MIM: #618947) is a rare congenital disorder arising from biallelic variants in TOR1A." (PMID 36757831, 2023).
Glutaric Aciduria type 1 (1 paper, 2023). "The genetic dystonias were associated with the following genes: TOR1A, THAP1, SGCE, KMT2B, HPRT1 (Lesch Nyhan disease), PANK2 and GCDH (Glutaric Aciduria type 1)." (PMID 36445406, 2023).
migraine with aura (1 paper, 2021). A migraine disorder characterized by episodes that are preceded by focal neurological symptoms. "Interestingly, several genes were abundantly expressed already during iDN differentiation and associated with migraine with aura such as HTT, TOR1A but also DRD2 which suggests a putative implication in the development of neural progenitor cells." (PMID 34486248, 2021).
peripheral nerve injury (1 paper, 2016). Injury to a peripheral nerve. "We hypothesize that Tor1a+/- mice on the other hand present a deficit in central inhibition that drives uncontrolled central DA efflux after peripheral nerve injury." (PMID 27716431, 2016).
movement disorder (18 papers, 2009 to 2026). Neurological conditions resulting in abnormal voluntary or involuntary movement, which may impact the speed, fluency, quality and ease of movement. "DYT1 early-onset generalized torsion dystonia (DYT1 dystonia) is an inherited movement disorder caused by mutations in one allele of DYT1 (TOR1A), coding for torsinA." (PMID 23967309, 2013). "DYT1 early-onset generalized torsion dystonia is an inherited movement disorder and is caused by mutations in DYT1 (TOR1A) coding for torsinA with about 30% penetrance." (PMID 21931745, 2011). "The mutated TOR1A gene causes generalised dystonia (DYT1), a movement disorder characterised by sustained or intermittent muscle contractions leading to abnormal repetitive movements and postures." (PMID 32365120, 2020). "Notably, although animals with the TOR1A mutation have significant striatal neurochemical abnormalities, they exhibit little to no phenotypic resemblance of a movement disorder." (PMID 32365120, 2020). "Most cases of early onset DYT1 dystonia in humans are caused by a GAG deletion in the TOR1A gene leading to loss of a glutamic acid (ΔE) in the torsinA protein, which underlies a movement disorder associated with neuronal dysfunction without apparent neurodegeneration." (PMID 22611399, 2012).
neurodevelopmental disorder (4 papers, 2012 to 2023). A behavioral and cognitive disorder with onset during the developmental period that involves impaired or aberrant development of intellectual, motor, or social functions. "Since DYT1 dystonia is a type of neurodevelopmental disorders, Tor1a+/- mutation might lead to the pathogenic process through ER stress-dependent way." (PMID 34398825, 2021). "The most common genetic form of primary dystonia, DYT1 dystonia, is a neurodevelopmental disorder caused by an in-frame deletion (GAG, “ΔE”) in the TOR1A gene that results in the loss of a glutamic acid in the C-terminus of torsinA." (PMID 22393392, 2012).
autosomal recessive disease (1 paper, 2023). Autosomal recessive form of disease. "In summary, this systematic cross-sectional analysis of a large cohort of individuals with biallelic TOR1A variants across a wide age-range delineates the clinical and genetic spectrum of TOR1A-related autosomal-recessive disease and highlights potential predictors for disease severity and survival." (PMID 36757831, 2023).
cancer (1 paper, 2021). A tumor composed of atypical neoplastic, often pleomorphic cells that invade other tissues. "We found TOR1A as significantly up-regulated in the nodule “B” (x = 1.44), but not altered in the other two cancer nodules." (PMID 34209090, 2021).
muscular disorders (1 paper, 2021). "We discovered novel compound heterozygous mutation of dysferlin and the TOR1A ΔE mutation in the same family, causing two similar but distinct hereditary muscular disorders in siblings." (PMID 34276779, 2021).
TOR1A also shares sentences with these, for which no sentence is quoted: celiac disease (20 papers); neurological disorder (12); Parkinsonism (8); cervical dystonia (7); neurodegenerative disease (4); type 1 diabetes (4); amyotrophic lateral sclerosis (3); Autoimmunity (3); diabetes (3); laryngeal dystonia (3); Myoclonus (3); segmental dystonia (3); Alzheimer disease (2); autoimmune disease (2); cardiomyopathy (2); Hepatic steatosis (2); Huntington disease (2); infection (2); multifocal dystonia (2); muscular dystrophies (2); neuroblastoma (2); neuromuscular disease (2); spinal muscular atrophy (2); Adult onset (1); Anxiety (1); asbestosis (1); autism (1); autism spectrum disorder (1); autoimmune enteropathy (1); autosomal dominant disease (1).
A further 42 diseases each share a sentence with TOR1A in 1 paper.